KRAS (KRas proto-oncogene, GTPase)
Diseases named in the same sentence as KRAS in open-access papers (continued):
Sharing a sentence is not in itself a finding about the gene and the disease.
tumor (continued). "In KRAS mutant tumor cells, the deletion of SNORD50A and SNORD50B promoted tumorigenesis, and the deletion of SNORD50A and SNORD50B and KRAS mutation coexisted significantly in multiple tumor types." (PMID 34616746, 2021). "As a result, there is an urgent need to investigate new hybrid small molecules to alleviate tumor burden in patients with KRAS-EGFR mutations." (PMID 34769090, 2021). "Despite the potential of ddPCR to identify ctDNA KRAS mutations, most studies have analyzed KRAS mutations in ctDNA in order to verify the corresponding mutation in matched tumor tissues." (PMID 33673558, 2021). "One interesting exception is the well-known oncogene, KRAS, which promotes the continuous proliferation of tumor cells after acquiring a gain-of-function mutation." (PMID 33963274, 2021). "IGF-IR, MET, ERBB1/2, ERBB3, PDGFRa, AXL and FGFR1 have all been implicated in MEK-inhibitor resistance in KRAS-mutated tumors depending on the anatomical tumor type or specific cell line that was examined." (PMID 33924994, 2021). "This classification is mainly based on the molecular drivers (e.g. mutations and amplifications) of the different tumor types, such as KRAS mutants, BRAF V600E, and HER2 amplifications." (PMID 33691728, 2021). "The frequency of SAAHIGHALOX5LOW patients was twofold higher in KRAS mutated tumours compared to KRAS wild-type tumours (5/17 = 29% vs. 5/31 = 16% respectively)." (PMID 34203378, 2021). "In summary, combination treatment with oHSV and MEKi Trametinib enhanced virus replication mediated by down-regulation of STAT1 and PKR phosphorylation in BRAF V600E-mutated tumor cells as well as BRAF wt/KRAS-mutated tumor cells." (PMID 34578339, 2021). "In our cohort, the KRAS mutation rate was 86.75%, which is similar to the results in a public database of patients undergoing microdissection or with high tumor cellularity." (PMID 34368001, 2021). "Since dual silencing of FTs and GGTs has not shown deleterious effects in mice, combinatory therapy of FTIs and GGTIs or Dual Prenylation Inhibitors (DPIs) have been proposed for treating KRAS-mutated tumours." (PMID 34359657, 2021). "The high correlation in the genetic status of KRAS obtained between cfDNA and matched tumor tissue suggests that the KRAS variants identified in the cfDNA of our patient cohort accurately represent the tumor tissue." (PMID 34640513, 2021). "The most advanced is a RASMULTI(ON) inhibitor, active against tumours harbouring KRAS-G12D and KRAS-G12V mutations, although their portfolio also includes KRAS-G12D- and KRAS-G13C-selective inhibitors." (PMID 34200676, 2021). "Compared with a KRAS mutation from a primary tumor, ctDNA and exosome is a less invasive method of analyzing the genomic profiles of mutations across the tumor gene for monitoring from the patients." (PMID 34442609, 2021). "A single G12, G13, or Q61 activating KRAS mutation in tumor DNA was identified in all 14 patients (100%) with a mean VAF of 18.7% ± 18.2% (range: 3.2% - 60.2%)." (PMID 34298235, 2021). "Immune checkpoint inhibitors are more efficacious than chemotherapy in NSCLC patients with EGFR wild-type, KRAS mutation, and any PD-L1 tumor proportion scores." (PMID 33725808, 2021).
tumor (continued). "Since preclinical studies demonstrated that dual inhibition of MEK and Akt can abolish RAS signaling, selumetinib and MK-2206 have been combined to evaluate drug toxicities and anti-tumor activity in patients with KRAS mutations." (PMID 34946644, 2021). "Compared with KRAS-G12V mutations or wild-type tumor groups, CRC patients with KRAS-G13D mutations are insensitive to cetuximab therapy." (PMID 34607583, 2021). "Oncogenic KRAS mutations develop unique metabolic dependencies on nutrients to support tumor metabolism and cell proliferation." (PMID 34003553, 2021). "The interesting feature of tumor cells harboring KRAS mutations is that they develop, over time, escape mechanisms to break free from the KRAS activation status and undergo adaptative changes to became insusceptible to the drug." (PMID 35004317, 2021). "This has implications for responsiveness to therapy, as a large proportion (40%) of colorectal cancer has KRAS mutation, and immunovisibility of the tumour is essential for a good response to neoadjuvant therapy." (PMID 34256782, 2021). "Acquisition of activating mutations in KRAS is an early event during malignant transformation of nearly all PDACs that influence tumor initiation, progression, and maintenance." (PMID 33546284, 2021). "The five tumor tissues that were positive for KRAS G12C mutation by CRISPR–Cas12a included the three specimens that were positive by both PCR and direct sequencing." (PMID 33467412, 2021). "The KRAS allele comutation network found in the PAAD tumor samples demonstrated that many genes had detectable comutation interactions with multiple alleles, primarily of reduced comutation." (PMID 33753749, 2021). "A remarkably synergistic therapeutic efficacy was shown in vivo for BRAF wt/KRAS-mutated tumor models, when a combination of oHSV including PD-1 blockade and MEK inhibition." (PMID 34578339, 2021). "In fact, many mouse models of cutaneous squamous cell carcinoma take advantage of inducible mutations in KRAS along with mutations of specific tumor suppressor genes." (PMID 33801965, 2021). "Experiments in Drosophila melanogaster have also shown that inter-clonal cooperation between mutants harbouring an oncogenic KRAS mutation or inactivation of the tumour suppressor scrib can support tumorigenesis mediated by JNK and JAK/STAT signalling." (PMID 33594337, 2021). "circRNA_100859-miR-217-HIF-1α axis was associated with Tumor-Node-Metastasis stage and KRAS mutations, both of which are important to the potential of a tumor to metastasize." (PMID 34162394, 2021). "Pathways implicated in pro-tumor responses (e.g., KRAS and EMT pathways) were enriched in macrophages from SA-ESCC." (PMID 34697289, 2021). "To mimic the genetic landscape of human KRAS-driven cancers we chose to co-mutate the tumor suppressor LKB1 in RasLow and RasHigh tissue." (PMID 33514834, 2021). "Compared to wild type KRAS CRCs, KRAS mutated tumours showed a trend toward female patients (56.3% vs. 43.7%), patients with right-sided tumours (66.7% vs. 33.3%), and a moderately differentiated histology (53.6% vs. 46.4%)." (PMID 33979337, 2021). "A study showed that CD8-positive TILs were more numerous in patients who had smoking-related KRAS mutation and tumor mutations: K-RAS mutation." (PMID 34575691, 2021). "The increasing knowledge about new cellular processes associated with KRAS mutations in CRC is providing new potential targets to treat these tumours." (PMID 34359657, 2021). "A high correlation between KRAS variants detected in tumor tissue and cfDNA of CRC patients has previously been reported." (PMID 34640513, 2021). "KRAS-mutant NSCLC with KEAP1 mutations were mostly immune inert tumours, with low T cell inflammation and low expression of PD-L1 ligands." (PMID 34012925, 2021).
tumor (continued). "Right colon tumours were likelier to harbour KRAS mutations than left colon tumours; similar findings were observed in previous studies." (PMID 33979337, 2021). "In summary, the SMARCA4-deficient tumors with a KRAS oncogenic activation are associated with a better prognosis, as the tumor will be less progressive, low grade, and with lower tumor burden as compared to a SMARCA4 intact KRAS co-mutated NSCLC." (PMID 34440689, 2021). "This study identified potentially targetable genomic changes in 17% of patients, including a number of clinically relevant gene mutations and fusions in the 12% of patients harbouring KRAS wild-type tumours." (PMID 34956889, 2021). "This KRAS mutation was detected in both plasma and tumor tissue, which was in contrast to the present study." (PMID 33915745, 2021). "In conclusion, the prognostic and predictive values of KRAS mutations are affected by many factors, such as tumor type, stage, patient age, sex, the coexistence of mutations affecting other oncogenes or tumor suppressors, and treatment regimens." (PMID 34607583, 2021). "The classical subtype was characterised by the expression of the endodermal lineage-specifying transcription factor GATA6, KRAS dependency and better survival outcomes, whereas the QM subtype was associated with a high tumour grade and poor survival." (PMID 33406790, 2021). "Although inhibition of KRAS expression in mice causes tumor regression, tumors relapse and become KRAS-independent." (PMID 33674596, 2021). "For the KRAS mutation-positive group, the radiomic score consisted of the edema/tumor volume ratio (coef: −16.8) and the tumor number (coef: −1.06)." (PMID 33747933, 2021). "Potentially, the observation of these polymorphisms in tumor tissue would prove a significant association between KRAS rs712, rs61764370 and rs7973450 SNPs and LSCC clinicopathological features." (PMID 34828284, 2021). "It has been established that oncogenic KRAS mutations stimulate a tumor-promoting inflammatory microenvironment that differentiates these tumors from their RAS wild-type counterparts." (PMID 34063999, 2021). "Tumours in the CMS3 subtype are enriched for KRAS-activating mutations, which have been linked to distinct metabolic pathways." (PMID 33669775, 2021). "A growing number of studies have suggested that mutations in KRAS played an important role in tumor invasion, metastasis, and chemoresistance." (PMID 35047000, 2021). "Using a cut-off of 0.2% mutant allele frequency, which is the reported reliable mutation detection cut-off for this assay, 17/48 (35%) of the tumours were classified as harbouring an activating KRAS mutation." (PMID 34203378, 2021). "Taken together, these observations suggest that acquisition of the KRAS driver mutation represents a molecular abnormality that will drive increased SAA expression in a tumour microenvironment where ALOX5 expression is reduced." (PMID 34203378, 2021). "A specific mutation known as KRAS G12C is a major driver of tumor growth, occurring broadly across solid-tumor indications." (PMID 33928034, 2021). "They found an association between KRAS mutation and sporadic MMRd tumours and noted a preponderance of ARID1a pathogenic variants in their cohort." (PMID 34572765, 2021). "The lipoplex contained a plasmid encoding a short hairpin RNA that executes selective silencing of the mutated KRAS gene with tumor cell entry facilitated by facilitated by fusogenic liposomes." (PMID 34683931, 2021). "It suggested that MEKi Trametinib treatment preferred to enhance oHSV replication in KRAS mutated tumor cells compared with KRAS wt." (PMID 34578339, 2021).
tumor (continued). "The KRAS mutant in patients from a primary tumor was significantly higher in the ctKRAS G12D mutation in the buffy coat compared with those of ctKRAS wild type tumors (median: 0.99 vs. 0.34; p < 0.001)." (PMID 34442609, 2021). "Mutations in either KEAP1 or NFE2L2 were found only in KRAS-driven tumor in our cohort and were associated with upregulation of all 3 AKR genes." (PMID 34344431, 2021). "Yet the concordance of the detected KRAS mutation between primary tumor and ctDNA is unfavorable on the other hand, varying from 25–75 %." (PMID 33593396, 2021). "Given the predominant role of oncogenic KRas in tumor, therapeutic strategy either targeting the mutated KRas or inhibiting the excessive KRas signaling is valuable in the treatment of tumors." (PMID 35069209, 2021). "The type of KRAS variant detected in cfDNA by TST170 showed high concordance with those detected in tumor tissue (77%), and very high concordance with cfDNA analyzed by BEAMing (94%)." (PMID 34640513, 2021). "It would also be of interest to explore associations between KRAS mutation subtypes and tumour expression of programmed death ligand 1 (PD-L1), but we did not collect information on PD-L1 expression." (PMID 34503114, 2021). "On the contrary, the frequency of KRAS mutation was higher in progressed lung nodules, indicating a position for KRAS mutation in tumor progression." (PMID 34589430, 2021). "The increased probability of a KRAS G12C mutation in tumor samples that did obtain the allele compared to KRAS WT LUAD tumor samples is likely due to the strong association between this mutation and signature SBS4 induced by carcinogens in tobacco smoke." (PMID 33753749, 2021). "The KRAS gene can simultaneously harbor multiple mutations that can potentiate tumor-promoting activity." (PMID 33801965, 2021). "Since LKB1 and KRAS mutations in tumors are still considered as undruggable targets, genetic aberrations screening of clinical tumor specimens is being carried out gradually." (PMID 34735498, 2021). "Depletion of SOS1 or specific alterations in GEF function have been shown to inhibit proliferation of the tumor cells harboring a KRAS mutation, in contrast to cells harboring KRAS wild-type." (PMID 34063682, 2021). "The morphology of tumors formed by KRAS intact KC/KPC cells resembled moderately differentiated adenocarcinomas, whereas loss of KRAS resulted in poorly differentiated neoplasms." (PMID 33674596, 2021). "In 7 out of 60 patients (11.6% of total) the KRAS mutational profile was different from the primary CRC tumor tissue." (PMID 34811396, 2021). "The detection of KRAS mutations in these tumor types is a predictive biomarker for the anti-EGFR therapy." (PMID 33673558, 2021). "We found a striking stability of the mutated KRAS AF after re-implantation of the SR tumor in all treatment schedules tested." (PMID 34271981, 2021). "The SEER-Medicare linked database lacks information on the status of tumor mutations, including KRAS and NRAS (biomarkers of exclusion from anti-EGFR therapy), and BRAF (biomarker of poor prognosis)." (PMID 34910154, 2021). "In line with our in vitro findings, gene expression analysis showed that CRC tumor specimens from patients harboring KRAS mutations (n = 217) display significantly higher mRNA expression levels of AATs compared with KRAS WT patients (n = 317)." (PMID 34003553, 2021). "After a first mutation in KRAS, secondary ones in cell cycle regulators can contribute to the development of the tumor and the progression to a more aggressive one." (PMID 34440587, 2021).
tumor (continued). "The proportion of women with KRAS mutated tumours was higher compared to men (57% versus 43%, respectively, p = 0.042)." (PMID 34503114, 2021). "In PDAC, KRAS mutation is critical to control tumor metabolism through promotion of glucose uptake and channeling of glucose intermediates into the hexosamine biosynthesis and the nonoxidative arm of pentose phosphate pathway." (PMID 33390837, 2021). "Point mutations of the KRAS gene in tumor tissues were determined in advance using RASKET and ddPCR." (PMID 34675229, 2021). "KRAS mutations in CRC also promote tumor growth and cancer progression by rewiring glucose, amino acids, and lipid metabolism." (PMID 34887764, 2021). "Primary site in right colon (HR, 2.325; 95% CI, 1.178–4.588), larger tumor size (HR, 1.17; 95% CI, 1.02–1.3) and KRAS mutation (HR, 1.73; 95% CI, 1.03–2.8) were also significantly correlated with OS." (PMID 33869034, 2021). "The high mutational concordance between bile and tumor tissue indicates that liquid biopsy to extract bile ctDNA can be used to detect KRAS variants for the diagnosis and prognosis of BTCs." (PMID 34572808, 2021). "In particular HCT116 cells were sensitive to radiation and were the only ones to respond to the FOLFOX, inducing apoptosis and reducing tumor size due to the KRAS mutation (KRASG13D) that sensitized cells to the chemotherapy." (PMID 34074330, 2021). "KRAS mutation has been recently linked to CSCs‐like phenotypes, with functional characteristics of promoting tumor initiation, self‐renewal, and metastasis in CRC cells." (PMID 34288405, 2021). "We analyzed prognostic factors in 148 patients with SNADETs, focusing on TNM stage, the anatomical location of the tumor, KRAS mutation, BRAF mutation, Fn, mucin phenotype, and PD-L1 status." (PMID 34797780, 2021). "A tumor-derived fragment of the KRAS gene with point mutations in the twelfth codon not only causes the transformation of recipient cells in vitro, but also promotes tumor growth in vivo." (PMID 34830126, 2021). "From a clinical-molecular standpoint the therapeutically management of CRC focuses on main alterations found in the RAS family protein, where single mutations of KRAS are considered both the hallmark and the target of this tumor." (PMID 33917572, 2021). "Among tumor tissue KRAS/BRAF mutation carriers, tumor‐derived cfDNA was detected by droplet digital polymerase chain reaction (ddPCR) in plasma of 93% of CRC‐LM and 20% of CRC‐PM patients and in peritoneal fluid in all CRC‐PM patients." (PMID 33635598, 2021). "Fresh frozen EUS-FNA or surgical biopsies from PDAC patient tumours were used to screen for KRAS mutations." (PMID 34956889, 2021). "Radiologic TTV revealed this difference to be associated with a higher tumor load in patients harboring a KRAS A146 mutation (median TTV 672 cm3 [A146] v 74 cm3 [G12], P = .036)." (PMID 34820593, 2021).